GBP1 (guanylate binding protein 1)
Description:
Interferon (IFN)-inducible GTPase that plays important roles in innate immunity against a diverse range of bacterial, viral and protozoan pathogens. Hydrolyzes GTP to GMP in two consecutive cleavage reactions: GTP is first hydrolyzed to GDP and then to GMP in a processive manner. Following infection, recruited to the pathogen-containing vacuoles or vacuole-escaped bacteria and promotes both inflammasome assembly and autophagy. Acts as a positive regulator of inflammasome assembly by facilitating the detection of inflammasome ligands from pathogens. Involved in the lysis of pathogen-containing vacuoles, releasing pathogens into the cytosol (By similarity). Following pathogen release in the cytosol, forms a protein coat in a GTPase-dependent manner that encapsulates pathogens and promotes the detection of ligands by pattern recognition receptors. Plays a key role in inflammasome assembly in response to infection by Gram-negative bacteria: following pathogen release in the cytosol, forms a protein coat that encapsulates Gram-negative bacteria and directly binds to lipopolysaccharide (LPS), disrupting the O-antigen barrier and unmasking lipid A that is that detected by the non-canonical inflammasome effector CASP4/CASP11. Also promotes recruitment of proteins that mediate bacterial cytolysis, leading to release double-stranded DNA (dsDNA) that activates the AIM2 inflammasome. Involved in autophagy by regulating bacteriolytic peptide generation via its interaction with ubiquitin-binding protein SQSTM1, which delivers monoubiquitinated proteins to autolysosomes for the generation of bacteriolytic peptides (By similarity). Confers protection to several pathogens, including the bacterial pathogens L.monocytogenes and M.bovis BCG as well as the protozoan pathogen T.gondii. Exhibits antiviral activity against influenza virus.
Synonyms: hGBP1
Tractability: Small molecule: a structure with a bound ligand is known; it has a high-quality binding pocket. Antibody: UniProt places it where antibodies can reach, with high confidence; its Gene Ontology location is reachable by antibodies, with medium confidence. PROTAC: UniProt records ubiquitination sites on it; ubiquitination databases record sites on it; its protein half-life has been measured.
Gene: Protein-coding gene on chromosome 1 (89,051,505 to 89,072,769, reverse strand). Ensembl gene ENSG00000117228.
Subcellular location: Cytoplasmic vesicle membrane; Golgi apparatus membrane; Cell membrane; Cytoplasm, cytosol; Secreted
Pathways (Reactome):
Immune System: CASP4 inflammasome assembly; GBP-mediated host defense; Interferon gamma signaling; Regulation of GBP-mediated host defense
Disease: Enterobacterial factors antagonize host defense; NS1 Mediated Effects on Host Pathways
Gene Ontology:
Molecular function: actin binding; cytokine binding; enzyme binding; G protein activity; GDP binding; GDP phosphatase activity; GTP binding; GTPase activity; Hsp90 protein binding; identical protein binding; lipopolysaccharide binding; protein binding; protein homodimerization activity; spectrin binding
Biological process: cellular response to interleukin-1; cellular response to tumor necrosis factor; cellular response to type II interferon; cytolysis in another organism; defense response to bacterium; defense response to protozoan; innate immune response; negative regulation of ERK1 and ERK2 cascade; negative regulation of interleukin-2 production; negative regulation of protein localization to plasma membrane; negative regulation of substrate adhesion-dependent cell spreading; negative regulation of T cell receptor signaling pathway; non-canonical inflammasome complex assembly; positive regulation of pyroptotic inflammatory response; protein localization to vacuole; regulation of calcium-mediated signaling; regulation of protein localization to plasma membrane; defense response to symbiont
Cellular component: actin cytoskeleton; cytoplasm; cytoplasmic vesicle; cytoplasmic vesicle membrane; cytosol; extracellular region; Golgi apparatus; Golgi membrane; plasma membrane; symbiont cell surface; vesicle membrane
Genetic constraint (gnomAD): Loss-of-function variants: 64 observed, 70.45 expected, observed/expected ratio (o/e) 0.91, 90% interval 0.74 to 1.12. The upper end of that interval is the gene's LOEUF score, 1.12, which puts it in group 4 of 6, group 1 being the genes least tolerant of losing a copy. Missense variants: 630 observed, 715.5 expected, observed/expected ratio (o/e) 0.88, 90% interval 0.82 to 0.94. Synonymous variants: 250 observed, 267.16 expected, observed/expected ratio (o/e) 0.94, 90% interval 0.84 to 1.04.
Homologues: Orthologues: chimpanzee GBP1 (96% identical), dog GBP1 (80% identical), rabbit GBP1 (80% identical), pig GBP1 (78% identical), guinea pig GBP1 (77% identical), rat Gbp1 (72% identical), rat Gbp1 (70% identical), rat Gbp3 (65% identical), Drosophila melanogaster atl (19% identical). Paralogues in human: GBP3 (87% identical), GBP2 (76% identical), GBP5 (67% identical), GBP4 (55% identical), GBP7 (54% identical), GBP6 (52% identical), ATL2 (21% identical), ATL1 (20% identical), ATL3 (20% identical), RNF112 (12% identical).
Diseases named in the same sentence as GBP1 in open-access papers:
GBP1 is named in the same sentence as 158 diseases in open-access papers, as found by Europe PMC text mining. Sharing a sentence is not in itself a finding about the gene and the disease. The quoted sentences say what the papers report.
breast carcinoma (35 papers, 2013 to 2025). "Transcriptional and immunohistochemical profiling of patient samples has revealed that high GBP1 signatures were associated with tumor reduction in breast cancer and SKCM." (PMID 35222540, 2022). "GBP1 expression is associated with enhanced motility of lung cancer cells, treatment resistance in ovarian cancer, and better recurrence-free survival in breast cancer." (PMID 36187937, 2022). "While its contributions to prognostic factors across cancer types is varied, GBP1 has been associated with improved survival in breast cancer." (PMID 34189853, 2021). "Three of the members of this family are associated with breast cancer: GBP-1, GBP-2, and GBP-5." (PMID 35681772, 2022). "In breast cancer, GBP1 acts as a tumor suppressor and its high expression correlates with significantly improved survival, but it can also promote brain cancer metastasis in growth factor-driven breast cancers." (PMID 40564939, 2025). "For instance, GBP1’s pro-metastatic role in breast cancer involves T lymphocytes facilitating brain metastasis, contrasting its anti-proliferative effects in colorectal cancer, driven by differential TME composition and cytokine profiles." (PMID 40564939, 2025). "In previous work we found upregulation of GBP1 in breast cancer cells following co-culturing with activated T lymphocytes." (PMID 39262976, 2024). "GBP-1 is a constituent of gene signatures that exhibit a positive correlation with enhanced prognosis of breast cancer." (PMID 38460960, 2024). "GBP1 total protein expression was higher in primary tumors, including breast cancer (p = 0.044), colon cancer (p < 0.001), KIRC (p < 0.001), and ovarian cancer (p = 0.001), than corresponding normal tissues." (PMID 35222540, 2022). "This is despite the fact that GBP-1 can inhibit tumor angiogenesis, inhibit breast cancer proliferation, and directly inhibit actin polymerization." (PMID 35681772, 2022). "If GBP-1 directly participates in breast cancer progression and/or prognosis as a single gene product, it would be expected to be prognostic as an independent indicator." (PMID 35681772, 2022). "GBP1 expression was also correlated with metastasis in both lung and breast cancers, where lung adenocarcinoma cells and brain-metastasizing breast cancer cells showed decreased migration after silencing of GBP1." (PMID 35222540, 2022). "When a large cohort of breast cancers of all types and stages were examined, GBP-1 correlated with poor RFS." (PMID 35681772, 2022). "GBP-1 correlates with significantly poorer RFS when examined as a single gene for a cohort of breast cancer patients that contains all forms of breast cancers." (PMID 35681772, 2022). "While our understanding of GBP-1, -2, and -5 in breast cancers is improving, much of what we know is still correlative." (PMID 35681772, 2022). "Recently, three members of the Guanylate-Binding Protein (GBP) family of interferon-induced GTPases, GBP-1, GBP-2, and GBP-5, have been implicated to play roles in breast cancer." (PMID 35681772, 2022). "Where GBP-1 is predictive of improved prognosis in breast cancers is when it is part of an IFN-γ gene signature." (PMID 35681772, 2022). "GBP1 overexpression has been reported to play the oncogenic role and predicts a poor prognosis in glioblastoma, breast cancer, HNSCC, esophageal SCC (ESCC), OSCC, ovarian cancer, and prostate cancer." (PMID 34439200, 2021). "In ER-negative breast cancer patients who developed brain metastasis, the GBP1 gene appeared to be upregulated by the stimulation of T lymphocytes, which promoted the ability of breast cancer cells to cross the blood–brain barrier." (PMID 33916322, 2021). "Increased GBP1 expression can inhibit cell proliferation in an inflammatory environment, while down-regulated GBP1 in various tumors such as melanoma, colon cancer, and breast cancer can help protect cells from the damage of inflammatory response." (PMID 33194692, 2020).
breast carcinoma (continued). "In the transplantable breast cancer syngeneic model TS/A, GBP1 overexpression resulted in reduced angiogenesis and tumor growth." (PMID 32093058, 2020). "With respect to tumors other than breast cancer, GBP1 is considered to act as tumor suppressor gene in colorectal cancer, and as an effector of EGFR-driven tumor cell invasion in glioblastomas." (PMID 29350274, 2018). "RT-PCR results confirmed that GBP1 expression is significantly upregulated in breast cancer cells after co-culturing with T lymphocytes." (PMID 29350274, 2018). "The GBP1 gene appeared to be up-regulated in breast cancer of patients who developed brain metastasis." (PMID 29350274, 2018). "To further confirm our findings, we validated the upregulation of GBP1 after co-culturing breast cancer cells with T lymphocytes by RT-PCR." (PMID 29350274, 2018). "Proteomics analysis of the tumor cells revealed Guanylate-Binding Protein 1 (GBP1) as a key T lymphocyte-induced protein that enables breast cancer cells to cross the BBB." (PMID 29350274, 2018). "Several top up-regulated genes were associated with motility, adhesion, invasiveness, and metastasis in breast cancer or other cancers, such as GBP1, ITGB6, ITGA2, and matrix metalloproteases MMP10 and MMP1." (PMID 27351228, 2016). "A pseudogene of GBP1 and its parent gene show statistically significant anti-correlation with hsa-mir-199a, which has been shown to regulate autophagy in breast cancer cells." (PMID 25765044, 2015). "In breast cancer, GBP1 promotes lymph node and brain metastasis with T lymphocyte support, enabling blood–brain barrier infiltration through cytoskeletal remodeling and immune interactions, driven by its granular cytoplasmic localization and interferon-induced expression." (PMID 40564939, 2025). "Furthermore, GBP1 expression is positively correlated with metastasis and progression to brain metastasis in patients with breast cancer." (PMID 40018406, 2025). "In addition, we monitored the expression of GBP1 that was found to be upregulated in breast cancer cells upon co-culturing with activated T lymphocytes in our previous work." (PMID 39262976, 2024). "Indeed, T lymphocytes were shown to promote BM in estrogen-negative breast cancer through the upregulation of guanylate-binding protein 1 (GBP1), which enhances the ability of breast cancer cells to cross the BBB." (PMID 37190188, 2023). "The results of IHC showed that GBP1 protein was overexpressed in tumor tissues of breast cancer, HNSC, renal cancer, and ovarian serous cystadenocarcinoma (OV) compared with normal tissues, and GBP1 protein was mainly located in the cytoplasm and membrane of tumor cells." (PMID 35222540, 2022). "GBP-1 is a part of gene signatures that correlate with improved breast cancer prognosis." (PMID 35681772, 2022). "One way that GBP-1 could promote a better prognosis in breast cancers is through its ability to inhibit angiogenesis." (PMID 35681772, 2022). "Besides, GBP1 and IFI27 were associated with the apoptotic biological process, and were related to breast cancer phenotype resistant to trastuzumab treatment." (PMID 32318098, 2020). "In an earlier murine mammary carcinoma transplantation model study, it was disclosed that interferon gamma-induced human GBP1 could inhibit the tumor growth, although the recent studies indicated its role of oncogene in breast cancer." (PMID 31998647, 2019). "Intriguingly, in breast cancer metastasis, it was found that GBP1 expression was induced in breast cancer cells by T-lymphocyte activity, showing that cancer-extrinsic processes may influence GBP1's context and function." (PMID 32117203, 2019). "Contradictory findings regarding the function of GBP1 in breast cancer also exist." (PMID 31998647, 2019). "Silencing of GBP1 significantly decreased the ability of breast cancer cells to cross the BBB." (PMID 29350274, 2018).
breast carcinoma (continued). "GBP1 protein was exclusively measured and identified in all three breast cancer cell lines that were co-cultured with T lymphocytes (P < 0.001), and the GBP1 gene was up-regulated in the primary breast cancer samples that developed brain metastasis (P < 0.05 and 1.5 fold change)." (PMID 29350274, 2018). "Silencing of GBP1 reduced the ability of breast cancer cells to cross the in vitro BBB model." (PMID 29350274, 2018). "In addition, immunohistochemical staining for GBP1 of 20 independent samples of which 13 developed brain metastasis showed positivity only in the ER- breast cancer samples of patients who developed brain metastasis." (PMID 29350274, 2018). "Moreover, we showed that GBP1 expression was controlled by epidermal growth factor receptor (EGFR) in breast cancer cell lines." (PMID 29115931, 2017). "We conclude that EGFR controls GBP1 expression in breast cancer cells." (PMID 29115931, 2017). "In addition, we demonstrated that GBP1 expression is controlled by EGFR signaling in breast cancer cells." (PMID 29115931, 2017). "Furthermore, we confirmed the EGFR-signaling-dependent expression of GBP1 in breast cancer cell lines via qPCR." (PMID 29115931, 2017). "Also, murine mammary carcinoma cells transduced with GBP1 tet-inducible gene, showed reduced growth into syngeneic mice upon doxycycline treatment, due to reduced angiogenesis and tumor cell proliferation." (PMID 27683036, 2016). "Our data suggest that several pathway members, such as Stat1, Ifngr2, Tgtp1, Ifit1, Gbp1 and Gbp3, may be suitable biomarkers for residual disease in breast cancer patients treated with cytotoxic chemotherapy." (PMID 23520493, 2013). "Moreover, mutations in the GBP1 gene are among those related to the tumorigenesis of breast cancer and the aggressive hormone-negative inflammatory subtype in particular." (PMID 29350274, 2018). "The predictive value of GBP-1 as a single agent in breast cancer appears to only be applicable to ER− and TNBC breast cancers." (PMID 35681772, 2022). "To clarify what we do and do not know about GBPs in breast cancer, the current literature on GBP-1, GBP-2, and GBP-5 in breast cancer has been assembled." (PMID 35681772, 2022). "Alternatively, GBP-1 correlates with significantly improved RFS, OS, and DMFS in both TNBC and ER− breast cancers." (PMID 35681772, 2022). "Within the IFN genes, GBP1, CXCL10, IRF1, and STAT1 were described previously to be part of a tumor relapse-free signature in breast cancer patients." (PMID 30486871, 2018). "We demonstrated that GBP1 expression correlates with EGFR expression (and protein levels) in both tissues and breast cancer cell lines." (PMID 29115931, 2017). "Moreover, we found specific upregulation of guanylate-binding protein 1 (GBP1) in the tumor cells crossing the BBB and we also demonstrated that GBP-1 was overexpressed in the primary breast cancer samples of those women who had developed brain metastases." (PMID 39262976, 2024). "The expression of GBP1 is under control of IFN-γ and blocking of the IFN-γ pathway with inhibitor doses ≥5 μg/ml significantly decreased GBP1 expression and significantly decreased passage of breast cancer cells through our in vitro BBB model." (PMID 39262976, 2024). "Significantly, treatment of a panel of breast cancer cell lines demonstrated that 50% of the cell lines (3/6) failed to induce the expression of GBP-1 upon IFN-γ treatment, indicating a defect in IFN-γ signaling." (PMID 35681772, 2022). "In breast cancers of these genetic backgrounds, GBP-1 expression is not sufficient to independently predict the outcome." (PMID 35681772, 2022). "Previous reports have shown that GBP1 upregulation predicts a poorer prognosis in different types of cancer, including TNBC, whereas a higher level of GBP2 correlates with a favorable outcome in breast cancer." (PMID 33916322, 2021).
breast carcinoma (continued). "The GBP1-involved PGG network also contained the pseudogene GBP1P1, which may have a ceRNA regulatory role in breast cancer and in some neurodegenerative diseases." (PMID 31029062, 2019). "Microarray analysis of Ifn-γ/Jak/Stat1 effector genes, such as Gbp1 and Gbp5, have grouped the pathway with estrogen receptor negative (ER-) and triple-negative (ER−/PR/Her2-) breast cancers." (PMID 23520493, 2013). "The recent finding that GBP-1 can be unregulated in breast cancer cell lines by epidermal growth factor receptor (EGFR) signaling might provide clues on why GBP-1 is not protective when all types of breast cancers are considered as a group." (PMID 35681772, 2022). "However, despite most of the evidence favoring a positive, if not protective, role for GBP-1 in breast cancer, there are some studies that suggest the contrary." (PMID 35681772, 2022). "Since some breast cancers are growth factor–driven, this may explain why GBP-1 is only correlated with improved prognosis in a subset of breast cancers without receptor amplification." (PMID 35681772, 2022). "Furthermore, staining for GBP1 was positive only in the samples of the primary breast cancers of the patients who developed brain metastases, while not in the samples of patients who developed metastasis to other organs." (PMID 29350274, 2018). "Unlike GBP-1, GBP-5 correlates with improved RFS and OS as a single gene in a cohort containing all breast cancers." (PMID 35681772, 2022). "Unlike GBP-1 and GBP-5, all the literature on GBP-2 and breast cancer indicates that it is protective." (PMID 35681772, 2022). "Both GBP-1 and GBP-5 are suggested to be potential drug targets in breast cancers, despite that there is no consensus on whether they are associated with better or worse prognoses." (PMID 35681772, 2022). "Like GBP-1, GBP-5 is not a good prognostic indicator in ER+ breast cancers." (PMID 35681772, 2022). "The silenced GBP1 breast cancer cells showed a significant decrease in the ability to cross the BBB following co-cultured with T cells as compared to siSham cells, or to breast cancer cells that were not affected by silencing." (PMID 29350274, 2018).